MRLN (myoregulin)
Description:
Inhibits the activity of ATP2A1/SERCA1 ATPase in sarcoplasmic reticulum by decreasing the apparent affinity of the ATPase for Ca(2+), thereby acting as a key regulator of skeletal muscle activity. Its high expression in adult skeletal muscle, suggests that it constitutes the predominant regulator of ATP2A1/SERCA1 in adult skeletal muscle. Also inhibits the activity of ATP2A2/SERCA2 and ATP2A3/SERCA3.
Synonyms: MLN; M1; MUSER1; Linc-RAM; LINC00948
Tractability: Antibody: UniProt predicts a signal peptide or a membrane-spanning region.
Gene: Protein-coding gene on chromosome 10 (59,736,692 to 59,756,041, reverse strand). Ensembl gene ENSG00000227877.
Subcellular location: Sarcoplasmic reticulum membrane
Gene Ontology:
Molecular function: enzyme inhibitor activity
Biological process: negative regulation of calcium ion import into sarcoplasmic reticulum
Cellular component: sarcoplasmic reticulum membrane; endoplasmic reticulum membrane
Homologues: Orthologues: macaque MRLN (96% identical), rabbit MRLN (89% identical), mouse Mrln (80% identical), rat Mrln (80% identical).
Diseases named in the same sentence as MRLN in open-access papers:
MRLN is named in the same sentence as 1 disease in open-access papers, as found by Europe PMC text mining. Sharing a sentence is not in itself a finding about the gene and the disease.
MRLN shares sentences with these, for which no sentence is quoted: tumor (1 paper).